EPHA2 (EPH receptor A2)
Diseases named in the same sentence as EPHA2 in open-access papers (continued):
Sharing a sentence is not in itself a finding about the gene and the disease.
breast cancer (continued). "Thus, the exosomal EphA2-mediated intercellular communications between drug-resistant cells and sensitive cells may be an important mechanism of drug resistance-induced breast cancer progression." (PMID 33879771, 2021). "Moreover, the activation of ERK1/2 signaling downstream of the reverse pathway may be related to the promotion of the invasion and metastasis of breast cancer cells by exosomal EphA2." (PMID 33879771, 2021). "For example, combined use of ALW-II-41-27 and WW437, a histone deacetylase inhibitor that could suppress phosphorylated EphA2 and EphA2 expression, results in remarkably increased effects on breast cancer cell growth and migration compared with either drug administered as monotherapy." (PMID 32811512, 2020). "Thus lack of E-cadherin expression in breast cancer cells caused improper localization of EphA2 to membrane ruffles, rather than to the cell-cell conjunctions and resulted in a metastatic phenotype." (PMID 27533087, 2016). "Doxazosin treatment resulted in activation of the pro-apoptotic receptor tyrosine kinase EphA2 and associated degradation of EphA2 that is characteristic to activated receptor tyrosine kinases, consistent with data obtained from prostate cancer (PC3) and breast cancer (MDA-MB-231) cells." (PMID 24516604, 2014). "Exploring the TCGA dataset from cBioPortal, we found that breast cancer patients with PTEN low and EphA2 high expression have the worst prognosis among the patients with different levels of PTEN and EphA2 expressions." (PMID 41130297, 2025). "EphA2, which belongs to the RTK family, is overexpressed in a variety of cancers, including lung cancer, breast cancer, and colorectal cancer." (PMID 38916835, 2024). "The same approach has been applied in breast cancer, with CAR-T cells targeting EphA2 and IL-13Rα2 effective in Her-2-enriched and triple negative breast cancer subtypes." (PMID 39596256, 2024). "The knockdown of EphA2 in cancer cells in vitro has exhibited significant effects in glioma, NSCLC and breast cancer cells." (PMID 38811954, 2024). "Overall, RNF5 modulates EphA2 level and tumor-suppressor function to facilitate tumor formation of HER2-negative breast cancers." (PMID 39596256, 2024). "Mass spectrometry analysis demonstrated that the E3 ligase RNF5 directly interacted with EphA2 and induced EphA2 ubiquitination and degradation in HER2-negative breast cancer cells, thereby suppressing EphA2 tumor-suppressive functions in this neoplasia." (PMID 39596256, 2024). "For example, in the context of MDA-MB-231 breast cancer cell lines, the engagement of the EA1.2 monoclonal antibody with the extracellular domain of EphA2 initiates receptor phosphorylation, culminating in its subsequent degradation." (PMID 38612592, 2024). "Here, KLF5 was proven to be a direct transcription factor for EphA2 in BLBC cells, and its expression was positively correlated in clinical samples from breast cancer patients." (PMID 37063424, 2023). "As a consequence, low RNF5 expression with high EphA2 expression exhibits tumor-suppressive properties and increased survival in estrogen receptor-positive HER2-negative breast cancers." (PMID 37816703, 2023). "As a consequence, increased EphA2 level and altered EphA2 phosphorylation induced by selective RNF5 inhibition decreases the tumorigenesis of HER2-negative breast cancers." (PMID 37816703, 2023). "Collectively, our findings suggested that the interaction of Shc3 with EphA2 and ErbB2 plays an important role in MDR and aggressive behavior of breast cancer." (PMID 36880347, 2023).
breast cancer (continued). "Our studies not only reveal the importance of RNF5 in regulation of EphA2 tumor-suppressive function in breast cancers, but also provide a promising clue to develop novel chemotherapy for ER-positive HER2-negative breast cancers." (PMID 37816703, 2023). "To further investigate the effect of RNF5-regulated EphA2 level, we measured EphA2 phosphorylation and several downstream pathways in RNF5 WT vs. KD breast cancer cells." (PMID 37816703, 2023). "In this study, we demonstrated that Shc3 acts as a novel binding protein of EphA2 and ErbB2 linking that activated Akt and MAPK pathways to mediate drug resistance and aggressive behavior in breast cancer." (PMID 36880347, 2023). "Previous research showed that EphA2 and ErbB2 can form a complex, resulting in increased activation of the RhoA GTPase and MAPK pathways in breast cancer cells." (PMID 36880347, 2023). "It was shown that both EphA2 and MT1-MMP are upregulated in different invasive breast cancer cells, and silencing the EphA2 or MT1-MMP gene inhibited collagen invasion of the cells." (PMID 36132127, 2022). "The receptor tyrosine kinase EPH receptor A2 (EphA2), a member of the Eph RTK family, is overexpressed in aggressive breast cancer and EphA2 forms a complex with ErbB2 thereby enhancing ErbB2-induced tumor onset and progression." (PMID 33946495, 2021). "However, whether exosomal EphA2 are involved in breast cancer progression remains unknown." (PMID 33879771, 2021). "In the UALCAN database, the mRNA expression of EPHA1, EPHA10, EFNA1, EFNA3, and EFNA4 was significantly higher, whereas that of EPHA2, EPHA4, EPHA5, and EFNA5 was significantly lower in breast cancer tissues than in paracancerous tissues." (PMID 33977106, 2021). "In breast cancer cells Ephexin4, a guanine nucleotide exchange factor (GEF) for RhoG, interacted with S897-phosphorylated EphA2 and mediated ephrin-independent cell migration, invasion, and resistance to anoikis." (PMID 33572284, 2021). "To test the role of EphA2 in bone metastatic disease in vivo, we used the MDA‐MB‐231 human breast cancer cells, which express high levels of EphA2,25, 38 to model experimental metastasis." (PMID 33869989, 2021). "Next, we determined the effect of exosomes carrying EphA2 and its mutants on the phosphorylation of ERK1/2 in breast cancer cells." (PMID 33879771, 2021). "It was shown that besides p38, MKK3 can bind to multiple other proteins, including several drivers of breast cancer, such as CDK4, AURKA, FGFR4, EPHA2, and MYC." (PMID 32873298, 2020). "For example, tyrosine-protein kinase receptor (EPHA2) is a prominent substrate of ACP1 and its kinase activity regulated by ACP1 can induce the cell transformation in breast cancer." (PMID 32787954, 2020). "First, we found that incubation of cells with different concentrations of EphrinA1 decreased the levels of EphA2, and CCND1 and c-MYC, consistent with previous reports showing an inverse correlation between EphA2 level and EphrinA1 in breast cancer cells." (PMID 30451837, 2018). "Among the family members, EPHA2 and EPHB4 are the most studied in breast cancer and additionally EPHA4, EPHA7 and EPHB6 emerged as promising clinical candidates in an expression profile of the individual EPH and ephrin family members." (PMID 26870995, 2016). "Although we found that EPHB2 was the most promising candidate in our breast cancer cohorts, EPHB2 together with EPHB6, EPHA2, EPHA4 and the ligands EFNB1 and EFNB2 were important to define prognostic relevant clusters." (PMID 26870995, 2016). "Similar enhancement effects in cell migration were reported following EphA2 expression in other cell types, including MDA-MB-231 breast cancer cells, PC3 carcinoma cells, U373 glioblastoma cells, and U87 glioblastoma cells." (PMID 22570727, 2012).
breast cancer (continued). "However, further study is needed to determine if EphA2 activity is affected by miR-26b in other cancers with high EphA2 expression, like breast cancer, colon cancer, and prostate cancer; and whether miR-26b-EphA2 dysregulation represents a new mechanism for cellular transformation." (PMID 21264258, 2011). "Furthermore, we confirmed that EPHA2 expression was higher in Basal like/TNBC, compared to the normal like and other BRCA subtype, according to TCGA Breast Cancer database using UCSC Xena platform." (PMID 40919148, 2025). "None of the screened breast cancer cell lines showed EphA2 protein regulation after insulin stimulation." (PMID 39572596, 2024). "Similarly, the E3 ligase RNF5 directly interacted with EphA2 and induced EphA2 ubiquitination and degradation in HER2-negative breast cancer cells, thereby suppressing EphA2 tumor-suppressive functions in this neoplasia." (PMID 39596256, 2024). "Aggressive breast cancer-derived cell lines, Hs578T, MDA-435, MDA-231 and BT549, showed increased levels of EphA2 receptor compared to human mammary epithelium-derived cell lines, MCF-10A, MCF-12A and MCF-10-2 where normal levels of EphA2 are expressed." (PMID 37530973, 2023). "To further investigate the effects of RNF5-regulated EphA2 in the tumorigenesis of breast cancer cells, we investigated whether RNF5 affects the adhesion of HER2-negative breast cancer cells." (PMID 37816703, 2023). "Thus we conclude that RNF5 limits EphA2 level and tumor-suppressive function to facilitate tumor formation of HER2-negative breast cancers." (PMID 37816703, 2023). "Importantly, approximately two-thirds of the breast cancers (3201/4934) in the analysis were ER-positive, HER2-negative, and better survival with high EphA2 expression was similarly observed in this subgroup of patients." (PMID 37816703, 2023). "Therefore, our studies indicate that RNF5 reduces the stability and cell surface distribution of EphA2 and maintains the balance of its phosphorylation to inhibit its tumor-suppressive function in HER2-negative breast cancers." (PMID 37816703, 2023). "Through clinical analysis, EphA2 was highly expressed in BLBC patients or triple-negative breast cancer (TNBC) patients based on DNA microarray data or TCGA data, and its high expression indicated a poor prognosis in breast cancer patients." (PMID 37063424, 2023). "Furthermore, the migration of breast cancer cells was measured in a transwell assay under conditions of RNF5 knockdown and/or EphA2 knockdown." (PMID 37816703, 2023). "Furthermore, Western blot analysis for EPHA2, EPHA4, and EPHA7 was performed in three different human breast cancer cell lines." (PMID 35204461, 2022). "EPHA2 activates AMPK signaling via the ligand Ephrin A1-dependent forward pathway to promote the tube-forming and migration ability of endothelial cells, thereby promoting breast cancer metastasis." (PMID 35673569, 2022). "In this study, exosomes rich in EphA2 significantly promote the invasion of breast cancer cells, whereas exosomes without EphA2 fail to enhance the invasive behavior in breast cancer cells." (PMID 33879771, 2021). "Though our models support a role for EphA2‐mediated IL‐6 osteoclast differentiation and osteolysis, we do not yet know if this regulatory pathway also mediates breast cancer cell homing to bone." (PMID 33869989, 2021). "Consistently, the CM from EphA2-silenced drug-resistant cells failed to increase the motility of breast cancer cells." (PMID 33879771, 2021). "In addition, treatment with EphA2-specific siRNA significantly reduces malignancy in glioma, non-small cell lung cancer (NSCLC), and breast cancer cells." (PMID 32811512, 2020). "Moreover, it has been reported that miR‐200a is related to the occurrence and development of endometrial cancer, breast cancer, and esophageal cancer by targeting genes, such as PTEN, EPHA2, and CRMP‐1." (PMID 30784214, 2019).
breast cancer (continued). "Especially EPHA2, EPHA4, EFNB1, EFNB2, EPHB2, and EPHB6 and their co-expression in breast cancer." (PMID 26870995, 2016). "Given the fact that EphA2 regulates tumor cell migration and invasion, our results suggest that it forms a molecular complex with CD44 through exon v10 and this promotes TN breast cancer migration." (PMID 24586375, 2014). "Given the fact that EphA2 plays a key role in promoting tumor invasion and metastasis, our results suggest a novel model of a molecular complex consisting of CD44 and EphA2 that facilitates TN breast cancer progression." (PMID 24586375, 2014). "Thus, we analyzed co-expression of ephrin-A1, the primary ligand for EphA2, and EphA2 protein in a large Stage I prognostic TMA from the NCI Cooperative Breast Cancer Tissue Resource (CBCTR) Cancer Diagnosis Program (CDP)." (PMID 21935409, 2011). "Flow cytometry analysis demonstrated that, in contrast to the normal cell line (HEK-293) or the EphA2-low-expressing cell line (MCF-7), the immunotoxin could bind significantly (approximately 99%) to the EphA2-overexpressing breast cancer cell line (MDA-MB-231) at a low concentration (2.5 ng/μL)." (PMID 40718433, 2025). "EphA2 regulates tumor-related neoangiogenesis, which is necessary for tumor maintenances through the PI3K signaling pathway EphA2 protein and mRNA, which are both highly expressed across multiple molecular subtypes of breast cancer (positive rate ~75% and ~84%, respectively)." (PMID 39795985, 2024). "Plasma EphA2 level was positively correlated with poor prognosis in patients with metastatic breast and was markedly higher than that in patients with nonmetastatic breast cancer." (PMID 37907962, 2023). "The activated receptor EphA2‐ErbB2 complex consequently recruits signaling molecules and activates MAPK and PI3K/Akt signaling cascades, and PI3K/Akt and MAPK pathway activation was related to drug resistance in breast cancer and its inhibitors provided a new effective drug discovery strategy." (PMID 36880347, 2023). "EphA2 was used as for antibody-based targeting because high levels of EphA2 expression are found on the most aggressive tumor cells and in the case of this study MDA-MB-231 was used as they are a model for more aggressive and hormone-independent form of breast cancer." (PMID 37530973, 2023). "In addition, HM-Exos from EPHA2 knockdown breast cancer cells failed to induce an upregulation of p-AMPK in endothelial cells." (PMID 35673569, 2022). "Moreover, they demonstrated that exosomal EPHA2 could activate the ERK1/2 signaling through the ligand ephrin A1-dependent reverse pathway instead of the forward pathway, advocating, as a result, breast cancer progression." (PMID 35408909, 2022). "EphA2 has also been related to breast cancer EMT and metastasis following elevated extracellular matrix rigidness; the process has been related to ligand-independent pathway and also occurs with engagement of LYN (Lck/Yes Novel) tyrosine kinase to S897-phosphorylated EphA2." (PMID 36142306, 2022). "Notably, the expression of EPHA2 was significantly higher in metastatic breast cancer compared with non-metastatic breast cancer." (PMID 35673569, 2022). "In line with this, down regulation of receptor expression with EphA2-specific siRNA oligos retarded tumor growth in pancreatic adenocarcinoma-derived cells and significantly reduces malignancy in glioma, non-small cell lung cancer (NSCLC;), and breast cancer cells." (PMID 33572758, 2021). "However, exosomes carrying EphA2-ΔL failed to promote the migration and invasion of breast cancer cells." (PMID 33879771, 2021). "Moreover, EphA2 has also been shown to mediate VEGF expression and VEGF-induced angiogenesis in breast cancer and pancreatic islet cancer cells, which suggests that EphA2 may promote the plasticity of tumor cells in some cases." (PMID 34476217, 2021).
breast cancer (continued). "In addition to bladder cancer, EphA2 overexpression is observed in numerous indications, including non-small cell lung cancer (NSCLC), breast cancer, gastric cancer, esophageal cancer, pancreatic carcinoma, colorectal cancer, prostate cancer, head and neck cancer, glioblastoma, and ovarian cancer." (PMID 33092175, 2020). "Therefore, 11 insulin-responsive cell lines were screened for insulin-induced EphA2 regulation, including four hepatoma (HepG2 WT, HepG2 IGF1R KO, Hep3B, and H4IIE), three acute myeloid leukemia (AML) (MOLM-13, THP1, and EOL-1), and four breast cancer cell lines (BT549, BT474, HCC38, and HCC1937)." (PMID 39572596, 2024). "Chromosomal rearrangements leading to the convergence of EphA2-SE with a specific oncogene EphA2 might be another common mechanism to boost PI3K/AKT and Wnt/β-catenin pathways and be shared between several oncological nosologies, namely colorectal cancer, breast cancer, cervical cancer, etc.." (PMID 38542080, 2024). "Interestingly, we found a high correlation on mRNA expression of ANXA1 and EphA2 in breast cancer patients (data not shown), indicating a possible regulation of ANXA1 could contribute to high level of EphA2, beside our mechanism reported here." (PMID 37063424, 2023). "However, whether and how EphA2 regulates basal-like breast cancer (BLBC) cell stemness and chemoresistance has not been revealed." (PMID 37063424, 2023). "Thus, EPHA2 is a potentially powerful biomarker for poor prognosis and progression of breast cancer, and targeting exosomal EPHA2-AMPK signaling may serve as a potential strategy for breast cancer therapy." (PMID 35673569, 2022). "Exosomal EphA2 activates ERK1/2 signaling through the ligand Ephrin A1-dependent reverse pathway rather than the forward pathway, thereby promoting breast cancer progression." (PMID 33879771, 2021). "Moreover, exosomal EphA2 activated ERK1/2 signaling through the ligand Ephrin A1-dependent reverse pathway rather than the forward pathway, thereby promoting breast cancer progression." (PMID 33879771, 2021). "However, our research extends this understanding by explicitly linking EPHA2 to the AKT/PI3K signaling pathway and demonstrating that its inhibition can enhance pyroptotic responses in breast cancer cells, a relationship that has not been thoroughly explored in prior research." (PMID 40919148, 2025).